COMP (cartilage oligomeric matrix protein)
Diseases named in the same sentence as COMP in open-access papers (continued):
Sharing a sentence is not in itself a finding about the gene and the disease.
tumor (continued). "The proteome of COMP-treated cells, both irradiated and non-irradiated, identify increased concentration of proteins associated with elevated tumor proliferation and aggressiveness." (PMID 40141111, 2025). "The COMP treatment and overexpression seem to have greatest effect on tumor responses when irradiated, and as such the degree of COMP expression in NSCLC may serve as a biomarker that predicts response to radiation therapy." (PMID 40141111, 2025). "Similarly, patients with COMP expression in the tumor stroma had a median OS of 0.6-year (p = 0.029) and a median RFS of 0.5 years, (p = 0.019) compared to 2.4 and 7.2 years respectively, in patients with COMP-negative tumor stroma." (PMID 38563861, 2024). "Moreover, despite understanding the role of COMP in extracellular matrix organization, its influence on the tumor microenvironment (TME) is not fully understood." (PMID 38615020, 2024). "Thus, when the paired samples (fallopian tubes / tumor samples) were analyzed with McNemar test, a gain of COMP expression was detected (p < 0.001) in the majority of tumor samples." (PMID 38615020, 2024). "Cartilage oligomeric matrix protein (COMP) is a novel regulator of the tumor microenvironment." (PMID 38563861, 2024). "Furthermore, COMP expression by cancer cells affects the cancer cell metabolism, increased resistance to apoptosis, and enhanced tumor metastasizing ability." (PMID 38563861, 2024). "Collectively, these observations indicate that the topology of COMP expression and its prognostic value is cancer-specific and might depend on the pathobiology of the tumor type." (PMID 38563861, 2024). "Indeed, we have previously demonstrated that the presence of COMP in the tumor microenvironment correlates with tumor fibrosis, which inhibits the infiltration of CD8-positive T-cells into the tumor." (PMID 38965233, 2024). "In addition, denser collagen fibers were present in the tumor microenvironment when COMP was detected in the tumor stroma." (PMID 38563861, 2024). "Moreover, the expression of COMP was correlated with a higher tumor grade irrespectively of the source of expression (p=0.045 for cancer cells and p=0.027 for the stroma)." (PMID 37207219, 2023). "The presence of COMP in the tumor stroma correlated with MSI (p=0.024)." (PMID 37207219, 2023). "In the current study, we aimed to examine the potential association between elevated levels of COMP in tumors from patients with CRC and levels of fibrosis, tumor-infiltrating populations of immune cells, and expression of PD-L1 on immune cells and tumor cells." (PMID 37207219, 2023). "Therefore, future experimental work is anticipated to elucidate how COMP activity restricts the immune response in the tumor microenvironment." (PMID 37207219, 2023). "Additionally, a negative correlation was identified between the expression of COMP and PD-L1 on both tumor cells and immune cells." (PMID 37207219, 2023). "Emerging evidence shows that COMP plays critical roles in tumor development." (PMID 35845304, 2022). "Targeting COMP or its interaction with other proteins may be a promising approach for preventing tumor progression." (PMID 36012514, 2022). "Moreover, tumor COMP expression is positively correlated with tumor size, lymph node metastasis, and advanced TNM stage." (PMID 36012514, 2022). "Above all, these results suggest that COMP may provide some theoretical support for tumor immunotherapy." (PMID 36551305, 2022). "In COAD and READ, the expression of COMP steadily increased as the tumor progressed." (PMID 36551305, 2022). "We also found that colony formation was decreased in cells with COMP knockdown, suggesting that COMP may promote tumor cell proliferation." (PMID 33613749, 2021).
tumor (continued). "In the tumor microenvironment of BC, a secreted protein named Cartilage Oligomeric Matrix Protein (COMP) physically bridges Notch3 and JAG1 on the cell membrane of CSCs, thus driving JAG1/Notch3 signaling and subsequently activating the β-catenin and Akt signaling pathways to maintain CSC status." (PMID 34195229, 2021). "Comparisons of IHC expression in cancer cells and stroma in primary tumors and LNMs with different clinicopathological variables showed a significant correlation of COMP expression in primary tumor cancer cells with age (p = 0.005) and in primary tumor stroma with MFI (p = 0.007)." (PMID 34884987, 2021). "Furthermore, when analyzing the survival from the date of primary tumor diagnosis, there was also a strong correlation between high COMP IHC expression in LNM and worse survival (p = 0.019)." (PMID 34884987, 2021). "Furthermore, there were significant correlations between high IHC COMP expression in the primary tumor cancer cells (p = 0.013) as well as in the primary tumor stroma (p = 0.013) and the presence of liver metastases." (PMID 34884987, 2021). "Background and Purpose: The role of the cartilage oligomeric matrix protein (COMP) in epithelial-mesenchymal transition (EMT) in tumor progression has been studied, but its exact regulatory mechanism remains unknown." (PMID 32754278, 2020). "The large tumor volume is not caused, as previously assumed, by COMP-induced extracellular matrix formation in the tumor stroma, as the tumor mass is mainly composed of tumor cells and less of stroma cells." (PMID 33227073, 2020). "Tumor weight decreased in the COMP knockdown group but increased in the COMP overexpression group." (PMID 32754278, 2020). "This indicates that measurement of serum COMP levels may be a more sensitive prognostic marker than immunohistochemical staining of tumor samples." (PMID 31737569, 2019). "Interestingly, when rh-COMP (10 μg/mL) was administered after CMCAFs + RvD1 treatment, the expression levels of EMT-associated markers, invasive capacity, cell viability, tumor sphere formation ability and CSC-associated markers were reversed (P < 0.05)." (PMID 30999932, 2019). "Serum measurements of COMP could allow a much easier evaluation compared with the more invasive immunohistochemical analysis of patient tumor tissues." (PMID 31737569, 2019). "In this study, we postulated that RvD1 could inhibit COMP secretion in CAFs in a paracrine manner via FPR2/ROS/FOXM1 signaling to block stoma-tumor cells interactions and then suppress EMT and cancer stemness to alleviate malignant progression of HCC." (PMID 30999932, 2019). "Additionally, COMP expression is associated with increased tumor invasiveness through integrin binding; inhibiting avβ3 and avβ5 receptors using cilengitide in DU145 cells treated with COMP reduced COMP-mediated integrin activation of the FAK/Src/AKT pathway, lowering invasion." (PMID 40141111, 2025). "Moreover, analysis of tumor tissues of high-grade serous tubo-ovarian cancer derived from the ScPanStroma database indicated that fibroblasts were the main stromal cell type expressing COMP." (PMID 38615020, 2024). "Notably, previous studies have demonstrated the tumor-promoting effects of COMP." (PMID 38584705, 2024). "Thus, COMP expression may contribute to immune checkpoint inhibitors resistance by immune exclusion of T-cells from the tumor compartment." (PMID 38563861, 2024). "Therefore, we aimed to assess the hypothesis that COMP expression in CRC leads to fibrosis-driven exclusion of tumor infiltrating immune cells." (PMID 37207219, 2023). "In the current study, we correlated COMP expression in the tumor stroma with fibrosis, which could prevent T-cells from infiltrating the denser stroma and eradicating the cancer cells expressing the neo-antigens, a phenomenon observed previously in urothelial cancer." (PMID 37207219, 2023).
tumor (continued). "In multivariable Cox proportional hazards analyses, COMP expression in the cancer cells (p=0.029) and in the stroma (p=0.021) was associated with reduced patient OS with a hazard ratio of 1.2, after adjustment for BRAF and KRAS mutations, tumor differentiation, TNM-stage, and vascular invasion." (PMID 37207219, 2023). "Moreover, increased COMP expression is associated with consensus molecular subtype 4 (CMS4) but not tumor location and KRAS mutant status." (PMID 36012514, 2022). "Furthermore, it has been reported that COMP is highly expressed in HCC tumor cells, indicating that it might also play a pathophysiological role in hepatocarcinogenesis." (PMID 34298722, 2021). "Expression intensities of SPARC, COL1A1, COL5A1, COMP, IBSP, and THBS4 were interpreted in tumor stroma, as they were associated with ECM-related pathways, and the expression intensity of SORD was interpreted in tumor cells, as it was associated with the EMT pathway." (PMID 34503278, 2021). "COMP, also referred to as thrombospondin 5, is a pentameric glycoprotein, which is expressed in cartilage and numerous other tissues/cells including ligaments, synovium, fibroblasts/myofibroblasts, vascular smooth muscle cells, cardiomyocytes, and various tumor cells." (PMID 31963737, 2020). "In addition, targeting stromal-derived COMP may be an effective strategy to block interactions between the tumor and stroma." (PMID 30999932, 2019). "Compared with normal tissues, the top three downregulated genes in the tumor tissues were FABP4, SAA1, and SFRP1, while the top three upregulated genes were COMP, COL10A1, and MMP11." (PMID 40936892, 2025). "COMP also has emerging roles in fibrotic tissues, vascular and ECM remodeling in traumatized tissues and in tumor biology." (PMID 41009743, 2025). "Further, in the entire cohort, the expression of COMP in the stroma was correlated with exclusion of different populations of immune cells (CD8+, CD3+, FoxP3+, CD20+) from the tumor microenvironment." (PMID 38563861, 2024). "Generally, THBS1 was primarily found in fibroblasts, endothelial cells, and mononuclear macrophage cells, THBS3 was mostly expressed in fibroblasts, tumor cells and T cells, whereas THBS2, THBS4 and COMP were mainly found in fibroblasts." (PMID 38827236, 2024). "As depicted in UMAP plots, THBS2, THBS4 and COMP were primarily expressed by fibroblasts, while THBS3 was predominantly expressed by tumor cells and fibroblasts, and THBS1 was predominantly expressed by fibroblasts, monocyte-macrophages and endothelial cells." (PMID 38827236, 2024). "Interestingly, COMP can stimulate tumor EMT, although the mechanism is unknown." (PMID 37838792, 2023). "COMP has also been shown to collaborate with the EMT pathway, leading to more aggressive tumor cells." (PMID 36999888, 2023). "The results revealed that SPP1, COMP, THBS2, SERPINE1, and COL11A1 were highly expressed in tumor tissues, while MYH11, TAGLN, and CNN1 were lowly expressed." (PMID 36999888, 2023). "COMP can enhance the ability of tumor cells to degrade ECM by upregulating the expression of MMP9, thereby, promoting EMT, which in turn promotes tumor invasion and metastasis." (PMID 37229458, 2023). "When COMP mRNA and protein expression were localized within the cytoplasm of the tumor cells by in situ hybridization and immunohistochemistry analysis, COMP was highly expressed within the tumor cells of HCC, suggesting that COMP might play a role in the pathophysiology of HCC." (PMID 35845304, 2022). "Most interactions were detected between fibroblasts, tumour cells and endothelial cells, and, in particular, the CAF FB_COL27A1, FB_SERPINE1 and FB_COMP were involved in most interactions." (PMID 34238352, 2021). "A cluster of genes that were upregulated in the tumours, compared to normal tissues were COL1A1, COL11A1, SPP1, COMP, SFRP4 and INHBA." (PMID 34824625, 2021).
tumor (continued). "ADAMTS12, is classified as proteinase of the cartilage oligomeric matrix protein (COMP), it is inducing neutrophil apoptosis in mice, and silenced ADAMTS12 genes were found in human tumor cells." (PMID 32817637, 2020). "COMP induced CD36-dependent activation of MEK/ERK and PI3K/AKT, and a panel of tumor-promoting factors, including EMT makers, MMP-2/9, Slug and Twist, so as to promote its tumor-promoting effects." (PMID 30231922, 2018). "Five genes (62.5%) demonstrated tumour acquired methylation (EMILIN2, SALL1, DBC1, FBLN2 and CIDE-A), whilst the remaining 3 (COMP, EPSTI1, SIM2) showed equal methylation in the corresponding normal breast tissue DNA." (PMID 20205715, 2010). "The tumor sphere formation assays also revealed a reduction in spheroid size upon treatment with DAPT (1 μM) or anti-Jagged1 antibody (2 μg/ml) in combination with COMP (20 μg/ml), compared to COMP-treated cells, for SKOV3 (COMP Vs." (PMID 38615020, 2024). "In the tumor microenvironment (TME) of GC, COMP was mainly expressed in the fibroblasts." (PMID 38584705, 2024). "COMP expression in the tumor stroma did not correlate with OS (p = 0.099) but with a shorter RFS (p = 0.042)." (PMID 38563861, 2024). "The only exception were patients with a primary tumor in the right colon, for whom the expression of high levels of COMP in cancer cells appeared not to influence the OS." (PMID 37207219, 2023). "The levels of serum COMP were higher in patients with ER- and HER2-positive tumors when compared to triple-negative tumors and correlated with the presence of bone and lung metastases, circulating tumor cell count, and clusters." (PMID 34884987, 2021). "Other significant DE genes with high FC(log2), unique to the study were INHBA, COL1A1, COL11A1, COMP, SFRP4 and SPP1, which were clustered in STRING network analysis and correlated with tumour-infiltrating immune cells in TIMER, suggesting a specific interaction pathway." (PMID 34824625, 2021). "The analysis of the corresponding tumor and non-tumor samples also revealed upregulation of COMP, matrix proteins such as COL5A1, COL11A1, and FN1, and genes of the Wnt pathway (WNT7B, FZD10, SFRP2), while PLCB1, CAMK2B, PLCB4 and WIF1 are downregulated." (PMID 33227073, 2020). "The cellular immunofluorescence experiments and SEM showed that COMP could interact with TAGLN to regulate cell remodeling and promote EMT in tumor cells." (PMID 32754278, 2020). "Moreover, the results of the tumor sphere formation assay showed that both the size and number of tumor spheres in Hep3B and SMMC-7721 cells were surprisingly decreased after co-culture with CMCAFs containing anti-COMP neutralizing antibody (P < 0.05)." (PMID 30999932, 2019). "Moreover, mRNA expressions of CA14, RPE65, IGSF1, SLC18 A2 and CPNE6 were significantly lower in PCa samples compared to benign samples, while HJURP, COMP, KRTAP5-1, VGF, SSTR1, LINC01612, NAALADL2-AS2, AMH and ARHGDIG were elevated in tumor samples (p < 0.05)." (PMID 40592939, 2025). "A similar phenomenon was observed in the group of collagen-COMP high tumors compared to collagen-COMP low tumors, irrespective of whether COMP was expressed by tumor cells or in stroma." (PMID 37207219, 2023). "Similarly, a trend was seen in shifts regarding COMP IHC cancer cell expression from the primary tumor to LNM, however this was not significant (p = 0.077)." (PMID 34884987, 2021). "Moreover, COMP expression in tumor tissues correlated positively with the presence of lymph nodes metastases, and estrogen/progesterone receptor positivity." (PMID 31737569, 2019). "In the entire cohort (n = 159), COMP expression by cancer cells was a negative prognostic marker for OS (p = 0.036) independently of primary tumor location, TNM-stage, tumor grade and Laurén type." (PMID 38563861, 2024).
tumor (continued). "The qRT-PCR analysis of 20 pairs of BC and adjacent non-tumor tissues showed that the expression of PDGFRB, COMP, GREM1, and FRRS1 was higher in BC tissues than in non-tumor tissues." (PMID 36895470, 2023). "Our findings revealed that the COMP expression levels were elevated in advanced T, N, and AJCC stage, but not related to age, gender, tumor location, tumor size, differentiation, N stage, and MSI status." (PMID 36671447, 2022). "All AC-NOS showed an overexpression of COMP, in ACC all tumors showed an overexpression except one, in MEC there were two tumor samples that showed no expression." (PMID 33227073, 2020). "In the tumor stroma, the IHC expression of COL5A1, COMP, and IBSP was significantly higher in the group with BM than that in the group without BM (p = 0.001 for COL5A1, p = 0.015 for COMP, and p = 0.003 for IBSP)." (PMID 34503278, 2021). "Antibody response against r-COMP was not correlated to tumor volume in the non-reactive FSPs pool group or reactive FSP group, indicating that anti-r-COMP immune response was not essential for tumor protection." (PMID 30478295, 2018).